CYP1A1 (cytochrome P450 family 1 subfamily A member 1)
Diseases named in the same sentence as CYP1A1 in open-access papers (continued):
Sharing a sentence is not in itself a finding about the gene and the disease.
cancer (continued). "In addition, AhR/CYP1A1 pathway-mediated epigenetic mechanisms play a significant role in regulating gene expression, self-renewal, and the chemoresistance of cancer stem cells in a variety of human malignancies." (PMID 39339278, 2024). "It is possible that the increased activity of the CYP1A1 enzyme may lead to the production of reactive metabolites that can damage DNA and promote the development of cancer." (PMID 39769254, 2024). "Consequently, CYP1A1 expression detected in the cancer cells of some NSCLC samples was probably controlled by other transcriptional regulatory pathways that were not linked to activation of AhR signaling." (PMID 39199657, 2024). "Furthermore, CYP1A1/1A2- and reactive oxygen species (ROS)-mediated 2-hydroxylation reactions of Mel were verified to be the two metabolic pathways in the liver and cancer cells, respectively." (PMID 38293248, 2023). "This feature can be used in cancer therapy with prodrugs activated by CYP1A1 and CYP1B1." (PMID 37511239, 2023). "Importantly, proof-of-concept studies utilizing CYP1A1 for the development of cancer-targeted therapies have been conducted by many groups." (PMID 38001897, 2023). "However, overexpressed XRCC1 and CYP1A1 reversed the inhibitory effect of miR-486-3p mimic on cancer cells and tumors." (PMID 33500536, 2022). "AHR has been extensively studied in its relationship with CYP1A1 and cancer prevention." (PMID 34262928, 2021). "In addition to very rare germline variants in genes related to liver function, such as HOXC4, PRSS56, and CYP1A1, the patient carried two variants strongly predicted to be deleterious affecting BRCA1 and FAH, both genes associated with cancer predisposition." (PMID 32432034, 2020). "Importantly, the AHR is also constitutively active and overexpressed in many types of cancer, and CYP1A1 and CYP1B1 are overexpressed in many cancers." (PMID 32398692, 2020). "Another plausible explanation of the negative findings on rs2066853 polymorphism is that the solitary polymorphism in AhR merely influences the transcription of CYP1A1 gene but does not play a vital role in the subsequent pathway to cancer development." (PMID 33278884, 2020). "Inhibition of CYP1A1 expression could protect the liver and other organs against cancer progression." (PMID 27800121, 2016). "Therefore,the improved understanding of CYP1A1/1B1 regulation in female genital and colorectaltissues will help cancer prevention and/or treatment in these tissues." (PMID 29276805, 2016). "Therefore, in this study we have revealed a new mechanism of epigenetic regulation of CYP1A1 expression in human carcinoma cell lines derived from different types of epithelial cells." (PMID 25116688, 2014). "Since carotenoids are known to induce phase I enzymes, including CYP1A1, they may enhance cancer initiation under certain conditions." (PMID 24137426, 2013). "A significant association between metabolizing phase I genes (CYP1A1) and UADT cancers was found." (PMID 24151610, 2013). "This concept seemed substantiated by studies on mice with high levels of active CYP1A1 (due to a high affinity AHR), which were more susceptible to cancers and genotoxicity when the PAH was brought in direct contact with the corresponding organs, but not after oral, systemic application." (PMID 22442665, 2012). "Such inhibitors are thought to be potential anti-carcinogens if they could inhibit the activities of CYP1B1 and CYP1A1 to metabolize PAHs to toxic intermediates and/or decrease their ability to detoxify cancer drugs." (PMID 22686946, 2012). "Certain flavonoids are capable of inducing CYP1A1 activity via the AhR in cancer cell line models." (PMID 19531241, 2009). "Ultimately the contribution of CYP1A1 to cancer progression or prevention may depend on the balance of procarcinogen activation/detoxication and dietary natural product extrahepatic metabolism." (PMID 19531241, 2009).
cancer (continued). "In addition, it is becoming increasingly evident that CYP1A1 plays an important role in the detoxication of environmental carcinogens, as well as in the metabolic activation of dietary compounds with cancer preventative activity." (PMID 19531241, 2009). "Thus, further study is required to investigate the hypothesis that CYP1A1 may act as a new potential therapeutic target for various types of HO-1-activated carcinomas." (PMID 40175891, 2025). "The CYP1A1 gene was significantly correlated with the instruments chosen to estimate the parameters of tobacco and alcohol consumption (FTCD and AUDIT scores), confirming the already known statement that the dual use of these substances substantially increases the risk of developing cancer." (PMID 35409669, 2022). "Therefore, CYP1A1 may be of particular interest in understanding the mechanism of action of CKI on cancer cells." (PMID 32730293, 2020). "Induction of CYP1A1 and CYP1B1 by environmental xenobiotic chemicals or endogenous ligands through the activation of the aryl hydrocarbon receptor (AhR) has been implicated in a variety of cellular processes related to cancer, such as transformation and tumorigenesis." (PMID 31698770, 2019). "The induction of cytochrome P450 (CYP)1A1 and CYP1B1 by environmental xenobiotic chemicals or endogenous ligands through the activation of the aryl hydrocarbon receptor (AhR) has been implicated in a variety of cellular processes related to cancer, such as transformation and tumorigenesis." (PMID 31698770, 2019). "Therefore, in current study, we included both a normal cell line (BEAS-2B cells) and a carcinoma cell line (A549) and similar effects of low pH combined with B[a]P exposure on CYP1A1 mRNA expression, EROD activity and B[a]P metabolism were observed, although at a different pH." (PMID 28005143, 2017). "Therefore, the contribution of CYP1A1 to cancer progression or prevention may depend on the balance of procarcinogen activation/detoxification and dietary extrahepatic metabolism." (PMID 24391993, 2013). "Interestingly, CYP1A1 also exerts important functions in thedetoxification of environmental carcinogens and the metabolic conversion of dietarycompounds into substances with cancer preventive properties." (PMID 23445205, 2013). "However, a meta-analysis to investigate the relationship between CYP1A1 MspI and Ile462Val polymorphisms and overall cancer risk has not been performed." (PMID 24391993, 2013). "Background/Objectives: CEU-938, an innovative antimicrotubule prodrug bioactivated by cytochrome P450 1A1 (CYP1A1), represents a promising targeted alternative for cancer cells overexpressing this enzyme." (PMID 41901204, 2026). "RNA editing leading to I462V alteration in CYP1A1 is a high-frequent molecular event observed in NSCLC, significantly promoting the malignant phenotypes of cancer cells." (PMID 40175891, 2025). "Several studies have demonstrated differential expressions of CYP1A1 and CYP1B1 across various tumor types compared with normal tissue, suggesting their potential application in cancer prognosis and therapy." (PMID 41009721, 2025). "We determined the aggregate effect of combined risk genotypes identified in univariate Cox regression analysis for any cancer (CYP1A1 Msp1 rs4646903 GG and CDC25C rs3734166 GA) on the age of cancer diagnosis in LS." (PMID 39457514, 2024). "Further, our study aimed to characterize in GC how AhR and the AhR-related genes cytochrome P450 1A1 (CYP1A1) and P450 1B1 (CYP1B1) affect the mRNA expression of a panel of genes involved in cancer development and progression." (PMID 39200369, 2024). "The CYP1A1 and CYP1B1 then bioactivate pollutants into highly reactive and carcinogenic intermediates that initiate cancer." (PMID 38448800, 2024). "Conversely, some CYP450 enzymes, like CYP1A1, CYP1A2, CYP1B1, CYP2A6, and CYP2E1, have a role in the onset and development of many cancers by converting pro-carcinogenic substrates into carcinogens." (PMID 39062040, 2024).
cancer (continued). "Aberrant DNA methylation at several CpG sites related to smoking, including cg06639488 (EFNA1), cg12101586 (CYP1A1), cg14142171 (HLA‐L) and cg07932199 (ATXN2), were indicated with cross‐cancer carcinogenic effects." (PMID 37449541, 2023). "Either siRNA silencing or CRISPR-Cas9-based knockout of AHR prevented expression of CYP1A1, but amplified the expression of MMP9, CXCL12 and CXCR4 that contribute to the tumorigenesis and metastasis of the cancer cells." (PMID 37151890, 2023). "E319 can have side effects on human health through activation of inflammatory routes, generation of reactive species, induction of CYP1A1, activation of caspases and decreases in GSH/ATP levels, and triggering of the gradual development of cancers." (PMID 36981116, 2023). "Cancer cell viability, proliferation, migration, and invasion were promoted by overexpressed circFLNA, XRCC1, and CYP1A1 but inhibited by miR-486-3p mimic and circFLNA knockdown." (PMID 33500536, 2022). "CYP1A1 and CYP1B1 are members of the CYP1 superfamily and have important roles in cancer progression." (PMID 36234852, 2022). "In the early stages of cancer development after PAH exposure, CYP1A1, HO-1, NQO-1, and IL-6 were identified as exposure biomarkers." (PMID 36056034, 2022). "Cytochrome P450 1A1 (CYP1A1) belongs to one of the most active isoenzyme subfamilies and participates in the metabolism of xenobiotics and anti-cancer drugs." (PMID 34830558, 2021). "The treatment with essential oil indicated mitigation of cancer activity by aborting the mRNA of pro-apoptotic markers such as BCL-2, CASPASE-3, CYP-1A1, and NFκB." (PMID 35009072, 2021). "The metabolic genes, CYP1A1 and CYP1A2, were widely underexpressed in multiple cancer types, whereas CYP1B1 exhibited different alterations in expression patterns." (PMID 33842355, 2021). "Overexpression of CYP1A1 and CYP1B1 were reported in various types of cancer cells including breast cancer." (PMID 30728391, 2019). "In particular, the mammosphere (CSCs) of all cancer cells tested, with the exception of MDA-MB231, showed higher CYP1A1 mRNA levels than CYP1B1." (PMID 28103884, 2017). "Because of demonstrated unequivocal involvement in smoking-induced cancer in laboratory animals, four candidate genes––AHR, CYP1A1, CYP1A2, and CYP1B1––were selected for a clinical genotype-phenotype association study of HNSCC risk in smokers." (PMID 27894333, 2016). "The CYP1A1 TT and COMT LL genotypes had higher estradiol levels in c-cancer (p < 0.001 and p = 0.037, resp)." (PMID 26798414, 2016). "Two human carcinoma cell lines derived from different types of epithelial cells were analyzed for basal and PCB 126 induced CYP1A1 mRNA expression using qRT-PCR." (PMID 25116688, 2014). "CYP1A1 is a critical CYPP450 and studies suggest that a CYP1A1 polymorphism may be a risk factor for several malignancies even in the face of its role in detoxification of environmental carcinogens and metabolic activation of dietary compounds that protect against cancer." (PMID 24391993, 2013). "Flavonoids are known to act as inhibitors of CYP1A1 and CYP1A2 resulting in prevention of cancer by environmental carcinogens." (PMID 22864238, 2012). "Both PBQs had potent inhibition against the activities of CYP1A1 and CYP1B1, the latter which is known to be a universal marker for cancer and a target for drug discovery." (PMID 22686946, 2012). "Recent in vivo investigations suggest that CYP1A1 may function as a carcinogen-detoxication enzyme, whereas the paradoxical activation of natural dietary compounds with chemopreventative activity provides further insight into the cancer-protecting role of this enzyme." (PMID 19531241, 2009). "In conclusion, the results presented in this study provide more evidence about the potential of the cytochromes P450 CYP1A1 and CYP1B1 as targets in cancer therapy and prevention." (PMID 18454852, 2008).
cancer (continued). "In this study, we have analyzed the expression of AhR in a series of diffuse and intestinal gastric tumors, as well as the expression of xenobiotic metabolic enzymes such as cytochromes P450 (CYP1A1 and CYP1B1) and a large panel of genes known to be regulated by AhR in several cancers." (PMID 39200369, 2024). "In primary human hepatocytes and HepG2 cancer cells, it was demonstrated that DMU-212, a tetra-methoxy analog of resveratrol, was the most potent AhR activator and CYP1A1 inducer among 13 different hydroxy- and methoxy stilbenes, including cis- and trans-resveratrol." (PMID 39339278, 2024). "Specific genetic variations in CYP1A1 and CYP1B1 genes were found to be more prevalent in certain cancer patients compared with the control group, suggesting that these polymorphisms might contribute to an increased susceptibility to cancer." (PMID 39062040, 2024). "Expression and functional role of AhR, CYP1A1 and CYP1B1: Animal and clinical data provide evidence for the role of AhR in gastric tumorigenesis, implicating the receptor in the regulation of tumor growth, EMT, migration, invasion, and cancer aggression." (PMID 39200369, 2024). "Sinapic acid is a potent anti-oxidant used for the treatment of cancer, infections, oxidative stress, and inflammation; its anti-cancer mechanism works through the regulation of multiple proteins (CTNNB1, PRKCA, CASP8, SIRT1) and cytochrome enzymes (CYP1A1, CYP3A4)." (PMID 38999065, 2024). "In addition, these studies revealed that eIF5A, BRD9, XRCC1, CYP1A1, and CRABP2 were miR-486-3p-regulated cancer-promoting genes in NSCLC cells." (PMID 37508549, 2023). "This heterodimer targets downstream target genes, activating the corresponding genes' abnormal expression, such as cytochrome P450 1A1/ cytochrome P450 1B1 (CYP1A1/CYP1B1), ultimately leading to cell toxicity, interference with animal endocrine, immunotoxicity, and even occurrence of cancer." (PMID 36829212, 2023). "This correlation between CYP1A1, GSTM1, GSTP1, and GSTT1 seems to be important, once this balance between activation and detoxification of carcinogens can influence the development, progression, and prevention of cancer." (PMID 35409669, 2022). "Considering that the expression levels of WNK2, CYP1A1, PAX5, XRCC1, and TGM3 have been reported to be closely related to the development of cancer, we then detected the expression levels of these genes in SK-MES-1 and A549 cells after transfection of circFLNA and miR-486-3p mimic." (PMID 33500536, 2022). "This loop is autoregulated by AHR-dependent elevation of the AHR repressor, and CYP1A1 and CYP1B1 enzymes that metabolize kynurenine ligands to decrease their bioavailability, thus forming a cancer progression circuit where AHR-regulated CYP1B1 levels correlate with AHR activity." (PMID 36077068, 2022). "Family 1 Subfamily A Member 1 (CYP1A1) and Family 1 Subfamily B Member 1 (CYP1B1) might play a role in cancer pathogenesis and prognosis." (PMID 33906313, 2021). "It is well described that CYP1A1, CYP1A2, and CYP1B1 play an important role in the detoxication of environmental carcinogens and in the metabolic activation of dietary compounds with cancer preventive activity." (PMID 33219472, 2021). "CYP1A1 synthesizes the pro-metastatic arachidonic acid metabolite 12(S)-HETE and is induced, e.g., by the activated aryl hydrocarbon receptor, the expression of which is high in many cancer entities and also in MDA-MB231 cells." (PMID 29593542, 2018). "In addition, resveratrol can inhibit 2,3,7,8-tetrachlorodibenzo-p-dioxin (TCDD)–induced expression of cytochrome P450 1A1 (CYP1A1) and 1B1 (CYP1B1), as well as their catalytic actions, in human breast epithelial Michigan cancer foundation (MCF)-10A cells." (PMID 29194365, 2017).
cancer (continued). "Interestingly, MCF-7 mammosphere cells showed the highest expression levels of CYP1A1 (27-fold) and CYP1B1 (7-fold) than corresponding adherent cells among all cancer cells, followed by T47D (20-fold for CYP1A1 and 4-fold for CYP1B1)." (PMID 28103884, 2017). "These natural inhibitors of CYP1A1 and CYP1A2 could have an important role in cancer prevention by reducing the metabolism of procarcinogens by these enzymes." (PMID 28698457, 2017). "In conclusion, the present data suggested that fucoxanthin inhibits CYP1A1, CYP1A2 and CYP3A4 enzyme activity and that these inhibitory effects may contribute towards the cancer preventive action of fucoxanthin." (PMID 24137426, 2013). "We chose to use the human cancer array and therefore changes in other metabolic genes such as CYP1A1, which is also known to occur upon 3-MC treatment, were not measured." (PMID 20178601, 2010). "Finally, our results are in line with the specific CYP1A1-dependent activation mechanism of PAIB-SOs, restricted to cancer cells expressing CYP1A1, and mostly absent in normal healthy tissues." (PMID 40006600, 2025). "The differential CYP1A1 and CYP1B1 expressions in normal tissues and tumour tissues may provide an opportunity for the development of tumour-selective drugs for the effective treatment of a variety of different cancers." (PMID 38257336, 2024). "Cytochromes CYP1A1, CYP1A2, and CYP1B1, the members of the cytochrome P450 family 1, catalyze the metabolism of endogenous compounds, drugs, and non-drug xenobiotics which include substances involved in the process of carcinogenesis, cancer chemoprevention, and therapy." (PMID 37511239, 2023). "The tryptamine receptor TAAR1 is a potential cancer prognosis biomarker and it could induce the transcription of the aryl hydrocarbon receptor (AHR) target gene cytochrome P450 1A1 (CYP1A1), leading to the activation of the conversion of organic compounds to cytotoxic or carcinogenic species." (PMID 36232383, 2022). "Thus CYP1A1 and CYP1B1 play essential roles in cancer therapeutics, as well as carcinogenesis." (PMID 24358191, 2013). "Hence, in the intact animal, intestinal CYP1A1 activity seems important in elimination and detoxification of PAH (and other toxic substrates of CYP1A1) and is, in all likelihood, an important factor in cancer prevention, especially when the activity of phase II enzymes is taken into consideration." (PMID 22442665, 2012). "As would be expected, high AHR expression and activity was usually, although not always, correlated with up-regulated CYP1A1 and/or CYP1B1 in cancers of the GI tract, bladder, head and neck, and breast." (PMID 33396563, 2020).